BRCA1 (BRCA1 DNA repair associated)
Diseases named in the same sentence as BRCA1 in open-access papers (continued):
Sharing a sentence is not in itself a finding about the gene and the disease.
breast cancer (continued). "In Vietnam, Ginsburg (2010) firstly found two (0.8%) BRCA1/2 gene mutations among 259 selected breast cancers in women." (PMID 35205313, 2022). "Overall risk for breast cancer and ovarian cancer is 55–70% and 40–45% for BRCA1 mutant carriers, respectively, and 45–70% and 15–20% for BRCA2 mutant carriers, respectively." (PMID 35163129, 2022). "Combined treatment with the EZH2 inhibitor GSK126 and cisplatin led to increased cytotoxicity and reduced colony formation in BRCA1-deficient mouse mammary tumor cells." (PMID 35715861, 2022). "Several PARPi have been approved for the clinical treatment of patients with BRCA1/2 mutations in pancreatic, prostate, ovarian, and breast cancers." (PMID 35332131, 2022). "Subsequently, the association of BRCA1/2 with mutation frequency alteration and copy number alterations in breast cancer was investigated using the cBioportal platform." (PMID 35409110, 2022). "The risk of breast cancer for BRCA1 and BRCA2 germline mutations among the carriers under 80 years of age is approximately 72% and 69%, respectively." (PMID 35300046, 2022). "Women carrying germline mutations in BRCA1 have a 50–80% lifetime risk of developing breast cancer and a 20–40% lifetime risk of developing ovarian cancer." (PMID 35453307, 2022). "Prospective studies have shown that mastectomy reduces the risk of breast cancer by 90% or more, with a residual risk of 1% to 2% in BRCA1 and BRCA2 mutation carriers." (PMID 36397405, 2022). "A small proportion of breast cancer has a familial predisposition, and genetic mutations such as BRCA1, BRCA2, and ATM can significantly increase the incidence of this type of cancer." (PMID 36473847, 2022). "The study group consisted of 330 women with pathogenic variants (PVs) in BRCA1/2 attending the dedicated multidisciplinary breast cancer clinic of a tertiary medical center in Israel." (PMID 35391652, 2022). "Germline BRCA1/2 mutation status is predictive for response to Poly-[ADP-Ribose]-Polymerase (PARP) inhibitors in breast cancer (BC) patients." (PMID 35662281, 2022). "BRCA1/2 mutation carriers with primary breast cancer (PBC) are at high risk of contralateral breast cancer (CBC)." (PMID 34929424, 2022). "Initially classified as an HR deficient cancer treatment, olaparib has been approved by FDA for the treatment of serous ovarian cancer as well as breast cancer having a mutation in BRCA1 or BRCA2 germline." (PMID 35873570, 2022). "Nonetheless, OPG is a promising biomarker for BRCA1-associated breast cancer risk due to the association between BRCA1 mutation and OPG levels." (PMID 35418083, 2022). "Early age of onset and a family history is a hallmark of hereditary breast cancer that is associated with germline variants in the high-penetrance genes, BRCA1 and BRCA24–6." (PMID 35039564, 2022). "One of the most studied tumor suppressors, BRCA1, has mutations that are closely related to the incidence rate of breast cancer and ovarian cancer." (PMID 36015648, 2022). "The role of BARD1 Cys557Ser varient or BARD1 haplotypes as modifiers of BRCA1/2 associated breast cancer risk was further evaluated in a cohort of 5546 BRCA1 and 2865 BRCA2 mutation carriers." (PMID 35650591, 2022). "In this review, we summarized the molecular functions and regulation of BRCA1 and discussed recent insights into the detection and treatment of BRCA1 mutated breast cancer." (PMID 35300412, 2022). "Recent cumulative risk estimates in high-risk families for developing breast cancer by age 80 years were 72% (95% confidence interval (95% CI, 65–79%)) for BRCA1 and 69% (95% CI, 61–77%) for BRCA2 pathogenic." (PMID 36203093, 2022).
breast cancer (continued). "In 70% of cases, breast cancer related to the germline BRCA1 pathogenic or likely pathogenic variant (gBRCA1) has an estrogen receptor-negative (ER-) phenotype." (PMID 35805038, 2022). "For example, females carrying genetic mutations in the genes BRCA1 or BRCA2 have a greater chance of developing breast cancer." (PMID 35495618, 2022). "This further supports that the BRCA1 mutation leads to profound epigenetic changes in BCs and that these changes have the potential to increase breast cancer risk." (PMID 35118379, 2022). "This miRNA affects cell proliferation and mutation in breast cancer by directly targeting the BRCA1." (PMID 36276982, 2022). "Mutations in the breast cancer susceptibility genes BRCA1 and BRCA2 confer a high predisposition to breast cancers and other tumour types, including ovarian, pancreatic, and colorectal." (PMID 35806243, 2022). "To investigate the effects of LRRC8A or LRRC8D defects on Pt drug sensitivity in HR-deficient tumors, we generated CRISPR/Cas9 KOs in cell lines derived from a genetically engineered mouse model for hereditary BRCA1-mutated breast cancer." (PMID 36467895, 2022). "BRCA1 deficient breast cancers are aggressive and chemoresistant due, in part, to their enrichment of cancer stem cells that can be generated from carcinoma cells by an epithelial-mesenchymal transition (EMT)." (PMID 35236825, 2022). "Here in this study, we use a novel method which based on whole-genome analysis to evaluate the chromosome instability (CIN) value and identified the potential relationship between CIN and prognosis of breast cancer patients with germline-BRCA1 mutation." (PMID 34403063, 2022). "Four recurrent loss-of-function variants were detected in 11 African-descended breast cancer cases, BRCA1:c.3331_3334delCAAG, BRCA1:c.211A>G, BRCA2:c.1389_1390delAG and PALB2:c.1671_1674delTATT." (PMID 35353237, 2022). "In the last few years, there has been increasing interest in using blood samples to measure DNA methylation in cancer studies, with the most robust candidate genes ATM and BRCA1 showing associations between breast cancer risk and methylation changes." (PMID 36076918, 2022). "BAP1 direct physical interaction with BRCA1-RING finger domain was associated to enhancement of BRCA1 tumour suppressor activity in breast cancer." (PMID 36318367, 2022). "A phase III clinical trial was conducted on patients newly diagnosed with ovarian cancer who also had breast cancer susceptibility (BRCA1/2) mutation." (PMID 36267984, 2022). "An MR study based on data from the BCAC, Biobank Japan, and Consortium of Investigators of Modifiers of BRCA1/2 also found that genetically proxied RA liability based on 25 SNPs was inversely associated with breast cancer in the East Asian population." (PMID 36514134, 2022). "To identify the factor which impact prognosis of breast cancer with BRCA1 germline mutation, we sought to determine the value of CIN in survival." (PMID 34403063, 2022). "The cumulative risk of developing breast cancer at the age of 70 for carriers of BRCA mutations is 65% for BRCA1 and 45% for BRCA2." (PMID 35744786, 2022). "Here, we depict an interplay of molecular, cellular, and tissue microenvironment alterations that increase BRCA1-associated breast cancer risk." (PMID 35393420, 2022). "Expression of USP1 has been found to be enriched in BRCA1-deficient breast cancers due to its promotion of RF protection." (PMID 36568963, 2022). "For BRCA1 mutation carriers, the risk estimate for breast cancer by age 80 is 72% and 44% for ovarian cancer." (PMID 35190584, 2022). "The patients with OC and breast cancer had predominantly BRCA1/2 pathogenic mutations, whereas only three out of 21 patients with OC and other tumors had a pathogenic variant." (PMID 36555431, 2022). "Another study found that mutated BRCA1 affects the expression of the β-subunit of human chorionic gonadotropin (β-hCG) in breast cancer." (PMID 35740092, 2022).
breast cancer (continued). "Another miRNA that is involved in breast cancer regulation is miR-155, known to bind BRCA1, a breast cancer susceptibility gene." (PMID 36076918, 2022). "Aside from those embryos with BRCA1 mutations, most embryos were predicted to have less than twofold OR of breast cancer, suggesting that PGT for breast cancer is most beneficial in scenarios with a pathogenic variant with high impact on disease risk." (PMID 35314819, 2022). "Patients with unilateral breast cancer carrying pathogenic variants in BRCA1/2 have the option to undergo contralateral prophylactic mastectomy (CPM)." (PMID 36685664, 2022). "All cases had a high risk of developing breast cancer due to a BRCA1 mutation; however, among the controls, there was one BRCA2 mutation carrier and the others had an increased risk due to familial predisposition." (PMID 36293255, 2022). "Together, these illustrate that loss of Brca1 in breast cancer cells enhances the CSC population and its property in tumor initiation." (PMID 35236825, 2022). "When a primary breast cancer is discovered and it needs to be surgically removed, individuals with mutations in the BRCA1/2 genes have two options: breast-conserving surgery (BCS) or radical mastectomy." (PMID 35805026, 2022). "To test this, we decided to evaluate the glycosylase OGG1 as a potential candidate, by treating BRCA1 proficient and deficient breast cancer cells with PARPi olaparib and the OGG1 inhibitor TH5478." (PMID 35619904, 2022). "Though BRCA1 mutation is the most susceptible factor of breast cancer, its prognostic value is disputable." (PMID 34403063, 2022). "Using this platform, we detected the breast cancer susceptibility gene 1 (BRCA1, a representative cfDNA closely related to breast cancer) that achieved a detection limit at the attomolar level." (PMID 35214994, 2022). "Meanwhile, male BRCA1/2 PV carriers are at a much lower absolute risk for breast cancer than females, although the relative breast cancer risk compared to the general population is higher in male versus female BRCA1/2 carriers." (PMID 36497436, 2022). "Significantly fewer patients in the intervention group mentioned that the possible higher risk of breast cancer for patients with EOC carrying a pathogenic BRCA1/2 variant was discussed during pre-test counseling." (PMID 36076240, 2022). "CNV deletions overlapping the lead candidate modifier SULT1A1 showed decreased breast cancer risk in BRCA1 pathogenic variant carriers." (PMID 36203093, 2022). "Germline mutations in the tumor suppressor gene BRCA1 (Breast Cancer 1, early onset) are associated with an increased lifetime risk for familial breast and ovarian cancers." (PMID 35837282, 2022). "Studies have shown that BRCA1 c.5470_5477del was a founder mutation in Chinese Han ovarian cancer patients and Chinese Han breast cancer patients." (PMID 35918668, 2022). "In recent years, a large increase in the use of multigene panel tests for breast cancer associated pathogenic variants (PVs) has expanded the number of potentially actionable PVs beyond BRCA1 and BRCA2." (PMID 33758026, 2022). "Since the effect of MYC overexpression on CD3+ TILs was most profound in the BRCA1-deficient mammary tumors, we further focused on the WB1P model." (PMID 36323660, 2022). "The BRCA1 DNA-repair-associated, breast cancer type 1 susceptibility (BRCA1) gene, which is important in the pathogenesis of a subset of breast cancer cases, was transactivated by VDR-induced factors." (PMID 35328609, 2022).
breast cancer (continued). "Some studies have reported that breast cancer patients who are germline carriers of pathogenic variants in DNA repair genes such as BRCA1 and BRCA2 are at higher risk of FN." (PMID 35681694, 2022). "A total of 1151 breast cancer patients having one or more high-risk clinical factors were enrolled for BRCA1 germline mutation screening." (PMID 34403063, 2022). "In this study, we evaluated multi-omic features of paired primary and recurrent tumors from 27 BRCA1/2 mutation carriers, representing 13 breast cancers (primarily TNBC) and 14 ovarian cancers (mostly high-grade serous)." (PMID 36344544, 2022). "On the other hand, the activity of 53BP1 is also required to maintain the efficiency of PARPi olaparib in BRCA1-mutated breast cancer cells." (PMID 36497275, 2022). "A recent increase in the use of multi-gene panels to screen for breast cancer-associated gene variants beyond BRCA1 and BRCA2 has started to identify PGVs in additional genes." (PMID 33763779, 2022). "Approximately 3% to 6% of all breast cancer cases are caused by a BRCA1/2 mutation (BRCA1/2mut), and women with a genetic BRCA1/2mut have a cumulative 45% to 66% risk of developing breast cancer by 70 years of age." (PMID 36358816, 2022). "BRCA1‐associated breast cancers are more likely to be invasive ductal type versus invasive lobular, tend to have a high mitotic rate and more frequently manifest a pattern of lymphocytic infiltration." (PMID 35128817, 2022). "On the other hand, women carrying BRCA1 mutations have a 50%–80% risk of developing breast cancer and a 40%–65% risk of developing ovarian cancer during their lifetime." (PMID 35517499, 2022). "Clinical management of women carrying a germline pathogenic variant (PV) in the BRCA1/2 genes demands for accurate age-dependent estimators of breast cancer (BC) risks, which were found to be affected by a variety of intrinsic and extrinsic factors." (PMID 35761208, 2022). "We subsequently examined the human cell type of origin of BRCA1-associated breast cancer for key protein expression or localization differences." (PMID 35393420, 2022). "Overall, we saw increases in the percent of enhancers that were proximal to ER-negative SNPs in each cell type due to BRCA1 mutation, suggesting an overall increase in breast cancer risk." (PMID 35118379, 2022). "This signaling was also linked to BRCA1-associated breast cancer risk with the identification of cGAS-stimulator of interferon genes (STING) and innate immune system-related gene sets in the analysis of the GWAS results." (PMID 35393420, 2022). "Key to this process is the breast cancer susceptibility genes BRCA1 and BRCA2 as well as the accessory RAD52 gene." (PMID 36530474, 2022). "BRCA1 is the most critical breast cancer hereditary susceptibility gene, which encodes homonymic proteins that serves in DNA repair processes during cellular stress." (PMID 34403063, 2022). "HR is an error-free repair and occurs mostly in cells in the S/G2 phase of the cell cycle; Breast Cancer Susceptibility gene 1 (BRCA1), Breast Cancer Susceptibility gene 2 (BRCA2), and RAS associated with diabetes protein 51 (RAD51) are important HR members." (PMID 34524579, 2022). "Poly ADP ribose polymerase (PARP) inhibitors (PARPi), such as olaparib, are the prototype of a synthetic lethality-based therapy, for example in breast cancers with BRCA1/2 gene mutations that exhibit homologous recombination repair (HRR) deficiency." (PMID 35022408, 2022). "Several genetic alterations are strongly associated with an elevated risk of breast cancer, of which BRCA1 (chromosome 17) and BRCA2 (chromosome 13) are the two important genes with great penetrance." (PMID 36110451, 2022). "BRCA1 mutations in breast cancer epithelial cells lead to the loss of H3K27ac at super enhancers and impair enhancer–promoter lopping, whereas BRCA2 depletion has been linked to chromatin remodelling." (PMID 35326684, 2022).
breast cancer (continued). "BRCA1 mutations are responsible for approximately 40% of inherited breast cancers and more than 80% of families with both inherited breast and ovarian cancers." (PMID 36942145, 2022). "The most prevalent germline mutations associated with breast cancer are breast and ovarian cancer susceptibility genes 1 and 2 (BRCA1 and BRCA2)." (PMID 36145297, 2022). "We found that both DNA repair and MKi67 expression were higher in high vs. low BRCAness group in BRCA1 mutation breast cancer in the TCGA cohort." (PMID 36371386, 2022). "We show that the combined treatment with the EZH2 inhibitor GSK126 and the ATM inhibitor AZD1390 led to reduced colony formation, increased genotoxic stress, and apoptosis-mediated cell death in BRCA1-deficient mammary tumor cells in vitro." (PMID 35715861, 2022). "Deletions overlapping BRCA1 increased breast cancer risk (hazard ratio (HR) = 1.29, 95%CI = 1.13–1.49, p = 1.98 × 10−4) for BRCA1 pathogenic variant carriers." (PMID 36203093, 2022). "Individuals with germline BRCA1 mutations have a 57‒72% lifetime probability of developing breast cancer, whereas those with germline BRCA2 mutations have a 45‒69% lifetime probability." (PMID 35907135, 2022). "Breast cancer patients carrying BRCA1 or BRCA2 germline mutations have a mean onset age of 40 and 43 years, respectively, and patients carrying PALB2 mutations have a mean onset age of 53 years." (PMID 35494038, 2022). "Talazoparib is a PARP inhibitor that is approved as monotherapy for the treatment of patients with HER2-negative advanced breast cancer with a germline BRCA1/2 mutation in the United States, United Kingdom, European Union, and other countries." (PMID 35907135, 2022). "BRCA1-deficient and -proficient mouse mammary tumor cells were treated with increasing concentrations of one compound in the absence or presence of a fixed concentration of the other compound and vice versa." (PMID 35715861, 2022). "It was also found to be associated with decreased BRCA1 expression in breast cancer cell lines, and with greater likelihood of having stage IV breast cancer." (PMID 35333900, 2022). "Approximately 5% of breast cancer patients carry a deleterious mutation in the Breast Cancer (BRCA1/2) genes, which are required for proper DNA damage repair and correlate with increased risk of developing breast cancer." (PMID 36387071, 2022). "Men with BRCA2 PV have approximately a 6% risk of breast cancer, for men with BRCA1 PV the risk is approximately 1%13." (PMID 35469032, 2022). "Missense polymorphisms can influence the transcriptional activity of the tumor suppressor gene BRCA1, increasing a woman’s risk of developing breast cancer." (PMID 36553064, 2022). "In comparison, a higher prevalence of 9.06-19.54% for BRCA1/2 mutation was observed in familial breast cancer patients." (PMID 36439508, 2022). "This class of medications is currently FDA approved for advanced, previously treated ovarian cancer with germline BRCA1/2 variants and previously treated metastatic HER2-negative BRCA1/2 variant breast cancer." (PMID 35685436, 2022). "The carrier of mutations in BRCA1/2 genes among women who have developed breast cancer by the age of 35 is about 10%, while for the general population it is about 0.2%." (PMID 35887761, 2022). "Hereditary breast cancer accounts for 30% of newly diagnosed breast cancer (BC) cases and is linked with germline pathogenic variants in the high-risk genes BRCA1 or BRCA2 in approximately 24% of cases." (PMID 35329227, 2022). "In unselected patients with breast cancer aged 35-64 years, pathogenic variants of BRCA1 and BRCA2 were detected in 2.4% and 2.3%, respectively." (PMID 36580360, 2022). "BRCA1 is a major breast cancer suppressor gene with a high mutation rate in hereditary breast cancer." (PMID 36193432, 2022).